BAX (BCL2 associated X, apoptosis regulator)
Diseases named in the same sentence as BAX in open-access papers (continued):
Sharing a sentence is not in itself a finding about the gene and the disease.
cancer (continued). "The consequent increased BCL-2/BAX ratio results in cancer cell evasion of apoptosis by inhibiting activity of the MPTP and MOMP and increasing Δψm." (PMID 33531986, 2021). "Increased levels of BAX, for example, were observed in cancer cells treated with Myricetin, Vitexin, Quercetin, Apigenin, Genistein, Daidzein, Luteolin, Naringenin, and Taxifolin." (PMID 33918290, 2021). "In no other area of medical research have the effects of such work been felt, than in cancer research, through targeting the BAX-Bcl-2 protein-protein interactions." (PMID 34753495, 2021). "Normally, triggering mitochondrial apoptosis in cancer cell lines by both prodigiosin and PU-H71 necessitates BAX activation and downregulation of BCL2 to initiate cytochrome c release." (PMID 32895397, 2020). "Fucoxanthin loaded in NGs + GL with CS induced apoptosis through the suppression of Bcl-2, upregulation of BAX levels, and promotion of caspase-3 activity in analyzed cancer cells." (PMID 32859058, 2020). "ACER3 is associated with the AKT/BAX pathway and activates the S1P phosphorylation of AKT through S1PR2 and PI3K in cancer cells." (PMID 32498325, 2020). "In the present study, we found that several chemotherapy drugs induced cancer cell pyroptosis were mediated by the BAK/BAX-caspase-3-GSDME pathway." (PMID 32332857, 2020). "Consistent with this evidence, we demonstrated that MD increases the BAX expression, promotes a mitochondrial membrane potential depolarization, and induces apoptosis in cancer cells." (PMID 32121436, 2020). "It induces the S1P phosphorylation of AKT through the S1P receptor 2 and PI3K and inhibits the AKT/BAX apoptotic pathway in cancer cells." (PMID 32498325, 2020). "Suppression of the anti-apoptotic proteins MCL1, BCL2, and BCL2L1 by BH3 mimetics has been well-known to induce the BAX/BAK-modulated mitochondrial death pathway of pro-apoptotic proteins in cancer cells." (PMID 32486166, 2020). "Obatoclax was originally described as a BH3 mimetic, which functions by binding antiapoptotic BCL-2 family proteins for displacing bound BH3-only proteins to initiate BAX/BAK-dependent apoptosis in cancer cells." (PMID 32150830, 2020). "Next, we individually compared the transcriptome profile between non-tumorous and tumor tissue to dissect differences during malignant transformation and identify potential molecular drivers in BAX-protected cancers." (PMID 32486514, 2020). "Herein, apoptosis was induced in human breast MCF-7 cancer cells by modulating the expression of BAX, CASPASE-3, SURVIVIN, and BCL-2 genes." (PMID 32020890, 2020). "In this study, we showed that TNFα+CHX and navitoclax-induced cancer cell pyroptosis through a BAK/BAX-caspase-3-GSDME signaling pathway." (PMID 32332857, 2020). "We are also showing that IRX1 expression is negatively associated with oncogenic hallmarks by GSEA and that IRX1 expression induces signs of apoptosis in cancer cells, including fragmented nuclei and BAX levels." (PMID 33256112, 2020). "A new class of anti-cancer drugs called ‘BH3 mimetics’ disturbs the sophisticated network of BAX/BAK-regulating BCL-2 family proteins and increases the readiness for mitochondrial cytochrome c release." (PMID 31324752, 2019). "At the same time, consistent overexpression and dysregulation were observed for BAX and Bcl-2, respectively, in all the cancer cells." (PMID 32010609, 2019). "On the other hand, a decrease of the expression of BAX was observed in all investigated cancer cell lines." (PMID 31801304, 2019).
cancer (continued). "The gene expression ratio BAX/BCL-2 indicated the induction of mitochondrial apoptosis in cancer cell lines." (PMID 30642021, 2019). "Among the cancer driver genes expressed in K-RMS-1 we found increments in the expression of BAX, RASD1, WT1, AKT1, cMYC and NOTCH." (PMID 30745580, 2019). "The analysis of the gene expression revealed that both compounds inhibited the proliferation in all cells (H3) and activated of mitochondrial events of apoptosis (BAX/BCL-2) in two cancer cell lines (SNB-19 and MDA-MB-231)." (PMID 31307242, 2019). "The role of BAX in drug-induced apoptosis in humancolorectal cancer cells identified lack function of BAX; in contrastabsence of BAX completely abolished apoptotic response." (PMID 31285648, 2019). "Whereas reports suggest that BAX gene surmount the effect of anti-apoptotic proteins and over expression of BAX gene can lead to apoptosis in cancer cells." (PMID 30876462, 2019). "A-1210477 also induced apoptosis in HCT116 cells deficient for BAX and BAK, demonstrating that this novel mechanism of apoptosis can also occur in a carcinoma cell line." (PMID 30796196, 2019). "In the context of cancer chemotherapy, BAX is likely the prime driver for certain cytotoxic agents to act 41,42." (PMID 30478310, 2018). "Several studies have reported that TIMP1 played a role in anti-apoptosis by suppressing BAX in cancer cells and mouse bone marrow stromal cell line." (PMID 29742163, 2018). "Overall, BAX SNPs is correlated with poor OS (HR = 1.735, 95% CI: 1.368–2.202, P = .000, AA + GA vs GG) in cancer, which indicates that someone who carries at least one variant gene has a negative impact on the survival." (PMID 30024563, 2018). "Altogether, these data demonstrate that S55746 kills cancer cells through on-target activity, meaning activation of a BAX/BAK-dependent mitochondrial apoptotic pathway by direct inhibition of the BCL-2 pro-survival protein." (PMID 29732004, 2018). "For example, increased expression of anti-apoptotic Bcl-2 proteins that block the action of pro-apoptotic effectors (BAX and BAK) has been associated with cancer cell progression and resistance to pro-apoptotic signals." (PMID 29156771, 2017). "Most targeted cancer therapies are based on stimulating the expression of BAX protein and/or suppressing BCL-2 protein." (PMID 29340085, 2017). "As one of mitochondrial pro-apoptotic factors, BAX is under intensive investigations and has been shown to have special importance in cancer therapy by regulating its expression and activities." (PMID 28556798, 2017). "Previous studies have reported that a variety of genes regulated by CTCF, including RB1, TERT and BAX, are involved in proliferation and apoptosis in cancer cells." (PMID 28977939, 2017). "BAX, or sorafenib, is another orally available, approved drug for treatment of different cancers, including advanced renal cell carcinoma." (PMID 28620943, 2017).
cancer (continued). "The anti-apoptotic factor Bcl-2 (B-cell lymphoma 2), an integral outer mitochondrial membrane protein, is also increased in cancer cells, while the pro-apoptotic protein BAX is downregulated." (PMID 30873475, 2017). "Among these BH3 mimetics, the synthetically derived ABT-737 has been shown to induce BAX/BAK-dependent apoptosis in a variety of cancer cell lines in vitro, and to display antitumor effects as a single agent in vivo." (PMID 26230693, 2015). "It has been therefore recognized that displacement of BH3-only proteins from Bcl-2/Bcl-XL or direct activation of BAX or BAD through BH3-mediated interaction is a major molecular mechanism for Gos-induced apoptosis in cancer cells." (PMID 25231749, 2014). "We observed a concentration-dependent increase in the number of detached cells for both HCT116 BAX+/− and BAX−/− cancer cell lines." (PMID 24185264, 2013). "Gain of 19q would result in increased copy number of several well known genes with involvement in cancer, such as BAX, CEACAM1, AKT2 and BCL2L12." (PMID 24144331, 2013). "In cancer clusterin inhibits apoptosis through its suppression of proapoptotic BAX and activates the PI3K/AKT cell survival pathway." (PMID 22989709, 2012). "The expression of BAX, a pro-apoptotic, inner mitochondrial membrane protein, is also reduced in some cancer cell-lines." (PMID 20426862, 2010). "Upregulation of BAX is crucial for the initiation of apoptosis in cancer cells." (PMID 39857977, 2025). "As one of the effects of inhibiting BAK/BAX is attenuating the apoptosis, it also needs to be noted that BAK/BAX inhibition might cause certain cancers." (PMID 41514922, 2025). "BAX activation induces mitochondrial outer membrane permeabilization, followed by the release of cytochrome c and other pro-apoptotic factors, leading to cancer cell death." (PMID 39860065, 2025). "Moreover, the molecular level and signalling investigations to identify how ABL can elicit the BAX expression in the cancer cells will be the next step." (PMID 39821171, 2025). "This could be confirmed by measuring whether GT-induced BAX/BAK activation in cancer cells is followed by extracellular secretion of mitochondrial DAMPs." (PMID 41304887, 2025).
cancer (continued). "Additionally, MOMP caused by BAX/BAK can lead to the release of mtDNA and mt-dsRNA into the cytosol, activating the cGAS/STING and RIG-I/MAVS pathways within cancer cells, which elicits the secretion of type I IFN cytokines for ICD induction." (PMID 41304887, 2025). "Furthermore, in various cancer cells, overexpression of Bcl-2 inhibits BAX/BAK-dependent pore formation, resulting in resistance to anticancer therapies." (PMID 41226559, 2025). "However, the overexpression of BCL-2 can antagonize BAX, allowing cancer cells to evade apoptosis and continue proliferating." (PMID 39966442, 2025). "Thus, phosphorylation of BAX at Ser184 by protein kinase B (PKB), a serine/threonine kinase also known as AKT, converts pro-apoptotic BAX protein into an anti-apoptotic protein, thus inhibiting apoptosis in cancer cell lines." (PMID 39860065, 2025). "In addition, the effects of this formulation on cell apoptosis, cell adhesion, cancer cell migration, and BAX, Bcl‐2, and Caspase‐3 gene expressions were evaluated using flow cytometry, atomic force microscopy, scratch, and q‐real time PCR, respectively." (PMID 40444124, 2025). "Previous studies have shown that hispidulin induces apoptosis through BAX activation, leading to mitochondrial membrane potential (MMP) loss and cytochrome c release, as well as an increased BAX/Bcl-2 ratio in multiple cancer cell lines, including CNE-2Z, SMMC7721, PANC-1, and HT29 cells." (PMID 40141371, 2025). "Moreover, an increase of BAX/BCL-2 ratio in both cancer cells clearly supported the fact that these cells undergo apoptosis after BNHLE treatment." (PMID 40362409, 2025). "Concretely, DS2‐treated cancer cells (IC50 value of 4.12 μM for MGC‐803) have shown to undergo mitochondria‐mediated apoptosis related to reactive oxygen species (ROS) generation and B‐cell lymphoma 2 (BCL‐2) associated X (BAX) regulation." (PMID 38726411, 2024). "Meanwhile, we predict that BAX is a pan-cancer prognostic biomarker, and targeting BAX may be a viable therapeutic strategy for many cancers to enhance the efficacy of immunotherapy." (PMID 39074253, 2024). "An imbalance of protein BAX and BCL-2 expression may associate with the activation of the apoptosis process in cancer cells." (PMID 38499634, 2024). "In order to determine whether LP treatment induces apoptotic cell death in HaCaT, A375, and MCF-7 cancer cells, the pro-apoptotic BAX and anti-apoptotic Bcl-2 levels were quantitatively measured using an in vitro enzyme-linked immunosorbent assay (ELISA)." (PMID 38258008, 2024). "The expression of BAX also regulates the sensitivity of cancer cells toward the immune system." (PMID 39074253, 2024). "We found that BAX expression is up-regulated in most cancers." (PMID 39074253, 2024). "For the first time, we revealed the remarkable relationship between BAX methylation and cancers, and BAX methylation level could be used as a biomarker for the prognosis." (PMID 39074253, 2024). "Furthermore, we assessed the correlation between BAX expression and 28 types of TILs in human cancers." (PMID 39074253, 2024).
cancer (continued). "Next, the in vitro experiments revealed that the tsRNA-GlyGCC inhibitor suppresses cell proliferation, migration, and formation of tumor spheres by modulating the protein expression of BCL2, BAX and cancer stem cells molecular markers (CD44,CD133, EphB2, LICAM, and LGR5)." (PMID 39153969, 2024). "Moreover, we demonstrate a rational strategy to identify BAX dimer modulators and potentially a new class of pro-apoptotic drugs for cancer therapy." (PMID 38104127, 2023). "Thus, our findings provide mechanistic insights into the regulation of BAX and resistance to apoptosis in cancer through inactive BAX dimerization." (PMID 38104127, 2023). "Furthermore, the discovery of BDM19 offers a chemical probe for investigating the role of cytosolic inactive BAX dimers (wild type or mutant) in cancer and potentially other homeostatic and pathological cellular contexts." (PMID 38104127, 2023). "For example, BAX expression among cancer cells is lowest in upper aerodigestive lineages (UAD) and highest in fibroblast lineages; CDKN1A is lowest in blood and highest in fibroblasts; GDF15 is lowest in lymphocytes and highest in kidney; and MDM2 is lowest in thyroid lineages and highest in cervix." (PMID 36681780, 2023). "These events were not a consequence of cell death, as BAX/BAK-deficient cancer cells exhibited similar downregulation of mTORC1 activity and MCL-1-protein levels." (PMID 37684238, 2023). "Further, to evaluate the mechanism of cancer cell death via checking the gene expression, HGRCm ZnO NPs upregulated the BAX and Caspase 3 and 9 expression levels but downregulated Bcl-2 expression, indicating that the nanoformulation induced mitochondrial-mediated apoptosis." (PMID 36677964, 2023). "Besides BAX mutations, phosphorylation has been described in specific BAX residues such as S184 through AKT kinase or T167 through JNK and p38 kinases in cancer cells." (PMID 38104127, 2023). "The reduction of cancer size may be explained by the downregulation of Bcl2 and up-regulation of BAX, which leads to a shift in the Bcl2/BAX ratio towards a pro-apoptotic signal in 7b-treated group." (PMID 35164019, 2022). "In summary, our study advances our understanding of cell death mechanisms in cancer cells and demonstrates a novel therapeutic strategy, which rationally targets pro-apoptotic BAX and anti-apoptotic BCL-XL to overcome apoptosis resistance mechanisms in a range of tumors." (PMID 35256598, 2022). "Moreover, Annexin V staining revealed that OLE induced apoptosis in cancer cells and upregulated the pro-apoptotic factor BAX." (PMID 35684123, 2022).